IDH1 (isocitrate dehydrogenase (NADP(+)) 1)
Diseases named in the same sentence as IDH1 in open-access papers (continued):
Sharing a sentence is not in itself a finding about the gene and the disease.
glioma (continued). "However, only a few studies have focused on IDH1 wild-type lower-grade glioma patients." (PMID 33229627, 2020). "In addition, IDH1 has the mutation of homologous gene, IDH2 mutation was also found in glioma." (PMID 32582544, 2020). "Finally, the elevated level of sPD-L1 after RT suggests that the combination of RT with immune checkpoint inhibitors may be a promising therapeutic strategy in gliomas, especially for patients with IDH-1 MUT gliomas." (PMID 33224142, 2020). "Therefore, patients with IDH1-mut glioma aged 48–63 years old might benefit from EGFR inhibitor therapy." (PMID 32819307, 2020). "Interestingly, the incidence of IDH1 and IDH2 mutations is elevated in gliomas." (PMID 32444979, 2020). "In recent years, immunohistochemical data using antibodies specific to IDH1 R132H mutant protein have revealed a more widespread tumor cell distribution than expected, including in the remote contrahemisphere, and have redefined high-grade glioma as a whole-brain disease." (PMID 32793462, 2020). "This suggests that the assessment of the status of BRAFAMP and IDH1/2 in adult glioma/glioblastoma patients has prognostic value as these patients have relatively short survival times and may benefit from personalized targeted therapy using BRAF and/or MEK inhibitors." (PMID 33489866, 2020). "Specific cancer cells, notably grade II/III glioma, secondary glioblastoma, and acute myeloid leukemia (AML) cells, exhibit heterozygous point mutations in the active sites of cytosolic isocitrate dehydrogenase isoform 1 (IDH1) or isoform 2 (IDH2), localized in the mitochondrial matrix." (PMID 31847543, 2020). "Taken together, these data suggest that decreased expression of miR-7156-3p may be involved in the glioma progression and patient survival independent of IDH-1 mutation." (PMID 33162825, 2020). "The observed changes were confirmed on the glioma tumor with and without the IDH1 mutation." (PMID 32392704, 2020). "For example, on the basis of mutations in the genes encoding the isocitrate dehydrogenases IDH1 and IDH2, co-deletion of 1p19q (oligodendroglioma) and methylation of O6-Methylguanine-DNA methyltransferase (MGMT) have been subclassified as molecular diagnostics and prognostic markers for gliomas." (PMID 33228738, 2020). "Thus, glioma cells with aberrant expression of EGFR have been shown preference for stiffer microenvironments, and softness of the glioma tissue positively correlated with higher tumor grade and IDH1 mutation." (PMID 33177991, 2020). "By combining tumor organoids of various glioma subtypes with in vivo expansion in the brain microenvironment, we present a cohort of 40 PDOX generated from primary and paired recurrent gliomas with mixed genetic backgrounds including, among others, IDH1 mutation and distinct EGFR variants." (PMID 33009951, 2020). "Comparison of DWI histogram profiles between low-grade gliomas with and without IDH-1 mutation." (PMID 32158691, 2020). "However, no significant miR-7156-3p difference was seen between glioma with or without isocitrate dehydrogenase-1 mutation (IDH-1)." (PMID 33162825, 2020). "Moreover, studies have shown that IDH1-mutant and wild-type gliomas are different disease entities." (PMID 33163535, 2020). "In addition, a study reported a glioma patient with BRAFV600E without the IDH1 mutation who experienced 2 years of overall survival." (PMID 33489866, 2020). "Moreover, based on DZIP3 expression, IDH1 wild-type lower-grade gliomas could be divided into two groups with different survival time." (PMID 33229627, 2020). "Moreover, here we show that highly active CASC2 significantly might have suppressed miR-21 levels in IDH1 wild-type gliomas." (PMID 33120918, 2020). "Finally, since it is suggested that hypermethylation caused by mutant IDH1 results in altered gene expression, usually their downregulation, we examined expression of additional genes described to be methylated in IDH1-mutant gliomas or in engineered IDH1-mutant cells." (PMID 32946483, 2020).
glioma (continued). "When comparing overall T-cell infiltration (CD3+) in primary glioma with and without the most common IDH1(R132H) mutation, we observed a significantly higher T-cell infiltration in IDHwt compared to IDHmut astrocytoma, which is in accordance with current literature." (PMID 33096928, 2020). "In conclusion, training a XGBoost classifier while using multiparametric radiomic features derived from DWI and FLAIR images discriminated IDH1 mutation status with accuracy > 90% and AUC > 0.95, which may provide an approach for noninvasive assessment of IDH1 status in patients with gliomas." (PMID 33121211, 2020). "A mutation in IDH1 is sufficient to induce genome-wide changes in DNA methylation patterns, including the glioma cytosine phosphate guanine (CpG) island methylator phenotype (G-CIMP) found in a subset of gliomas, which is associated with diverse transcriptional changes." (PMID 30857299, 2019). "While isocitrate dehydrogenase 1 (IDH1) expression has been confirmed in canine glioma via immunohistochemistry, further genome analysis has failed to reveal consistent mutations within the gene as opposed to human gliomas where IDH1 mutation is a common finding." (PMID 31788444, 2019). "We assessed the SWI signals of patients with gliomas to determine ITSS and pathological grades as well as expression levels of molecular markers, to assess correlations between ITSS grades and pathological grades, IDH1 mutation status, MGMT promoter methylation status, and 1p19q deletion status." (PMID 31745161, 2019). "Therefore, is the development of the IDH1/2 vaccine conducive to the treatment of glioma?" (PMID 31263678, 2019). "Moreover, the current Phase 1/2 study evaluated the safety, efficacy, PK, and PD of Olutasidenib (FT-2102, which is a selective potent inhibitor of IDH1) as a single agent and in combination with other anticancer drugs in patients with advanced solid tumors and gliomas." (PMID 31263678, 2019). "Similarly Tert promotor mutations are lacking and while R132 mutations of IDH1 have been noted rarely in canine glioma, they do not appear to have a cancer-promoting effect like they do in human glioma." (PMID 31788444, 2019). "Therefore, IDH1/2 is an important target for the prevention and treatment of glioma." (PMID 31263678, 2019). "The mutated IDH1 enzyme is not sufficient to catalyze the reductive carboxylation of α-KG to isocitrate, suggesting that this metabolic alteration contributes to the reduced aggressiveness of glioma cells expressing IDH1R132H." (PMID 31242696, 2019). "Furthermore, our results also imply that ALDOC mRNA and protein expression are inversely correlated with non-mutated IDH1 expression and play a good prognostic role in gliomas." (PMID 31450822, 2019). "To understand the metabolic state of human gliomas, we analyzed clinical samples obtained from surgical resection of glioma patients (grades II–IV) with or without the IDH1 mutation, and compared the results with U87 glioblastoma cells overexpressing IDH1 or IDH1R132H." (PMID 31278288, 2019). "Because the levels of malonyl-CoA were not increased in glioma samples with IDH1 mutation, fatty acid synthesis may not be activated." (PMID 31278288, 2019). "While in agreement with a recent study showing that TAGLN2 is a poor prognostic marker for gliomas, our study is the first to report that TAGLN2 is a negative prognostic factor associated with IDH1/2 WT gliomas and its regulation in gliomas is highly dependent on IDH1/2 mutation status." (PMID 30647847, 2018). "As a result, it would allow clinicians and scientists to stratify various management parameters such as urgency and extent of treatment (surgery, chemotherapy and radiation) and identify glioma mIDH1 subpopulations that may benefit more from the emerging class of IDH1-inhibiting drugs." (PMID 29303363, 2018).
glioma (continued). "However, more recent metabolomic studies of mutant IDH1 gliomas have suggested that 2-OG is rapidly replaced by glutaminolysis, and it is therefore unlikely that depletion of 2-OG could account for the loss of PHD activity seen." (PMID 29772792, 2018). "Therefore, IGFBP2 may be another potential biomarker for the distinction of the three glioma subtypes with positive IDH-1." (PMID 30322114, 2018). "Point mutations in IDH1/2 associate with longer survival and are found in about 80% of anaplastic astrocytoma (WHO Grade III) and secondary GBs (GBs that progress from lower grade gliomas), but only rarely (< 10%) in primary GBs (GBs that occur without precursor lesions)." (PMID 30211116, 2018). "The authors exploit a combination of computational methods, chromatin immunoprecipitation followed by sequencing (ChIP-Seq) to assess where on the DNA CTCF interacts, and publicly available data reporting changes to degrees of DNA methylation in glioma cells with or without the IDH1 mutation." (PMID 30405699, 2018). "The information gleaned from the methylation status and expression profile of the PD-L1 gene in gliomas is expected to help stratify patients, so that they can receive more appropriate and targeted treatment options, such as immune checkpoint inhibitors, that are specific for IDH1 wildtype gliomas." (PMID 29643764, 2018). "IDH1/2-mutant tumors tend to occur in the frontal or temporal lobe, and this information is valuable for predicting whether a lesion that appears to be a WHO grade II or III glioma harbors this mutation." (PMID 30082856, 2018). "Furthermore, our data suggest that while IDH1 mutant gliomas may have a less malignant phenotype, they may also be relatively resistant to certain therapies, including radiation." (PMID 29692895, 2018). "Demonstrating this negative association, we observed a significantly lower proportion of signature 1 mutations in IDH1 p.R132H mutant rather than wild-type brain lower grade glioma (P < 0.0001) and glioblastoma multiforme (P < 0.001) by two-sided Mann Whitney U-Test." (PMID 30412573, 2018). "It is not inconceivable that one day the IDH1 mutation subtype of glioma may influence the stratification of current management, particularly LGG and secondary glioblastoma." (PMID 29303363, 2018). "However, exogenously expressed mutant IDH1 may not recapitulate all the genetic and phenotypic changes that occur in IDH1-mutant gliomas." (PMID 30723695, 2018). "Further, specific heterozygous somatic point mutations of the isocitrate dehydrogenase gene (IDH1/2) were found in more than three-fourths of all oligodendrogliomas and nearly three-fourths of all astrocytomas of WHO grades II and III and in all 1p/19q codeleted gliomas." (PMID 29631562, 2018). "In addition, IDH1 mutant gliomas were more sensitive for Bcl-xl inhibition, which was shown to be dependent on D-2HG, which lowers Mcl-1 expression in mutant gliomas compared to wild type gliomas thereby increasing sensitivity for Bcl-xl inhibition." (PMID 30242253, 2018). "Regardless of the grade, IDH1/2 mutations are a favorable prognostic factor amongst all gliomas." (PMID 30647847, 2018). "Additionally, a recent study suggests that IDH1-mutant inhibitors may alter oxidative stress responses in glioma patients and therefore diminish the therapeutic efficacy of irradiation." (PMID 27852048, 2017). "However, MGMT expression is not the sole determinant of TMZ sensitivity and IDH1 mutant and wild-type gliomas have different molecular ontogenies, making comparisons between IDH1 mutant and wild type gliomas uninformative as to which tumor characteristics can be attributed directly to IDH1 mutation." (PMID 28178660, 2017). "However, the point mutations in IDH1 are characterized by loss of normal function and gain of an unusual new activity of reducing α-KG to d-2HG in an NADPH consuming reaction, thereby, exacerbating the already high oxidative stress in gliomas." (PMID 28346397, 2017).
glioma (continued). "The results from the BT142 IDH1 mutant tumor model reported herein, which shows similarity with the proneural subset of glioma patients from TCGA, represents an enticing potential opportunity for the application of a brain-penetrant IDH1 mutant inhibitor that may benefit patients clinically." (PMID 29062039, 2017). "In addition, we also investigated whether HOXA-AS3 affects IDH1 mutation and MGMT promoter methylation in glioma cells." (PMID 28881797, 2017). "Concerning immunotherapy, such approaches might only be feasible for IDH1-mutated low-grade gliomas, but not suitable for high-grade tumors." (PMID 29057925, 2017). "IDH1 (MRQ-67) rabbit monoclonal antibody is a specific marker for immunohistochemical detection of IDH1 mutant protein in glioma subtypes and may have value as a tool in distinguishing between diffuse astrocytomas and oligodendrogliomas from secondary glioblastoma." (PMID 31548536, 2017). "Therefore, IDH1, PTEN and EGFR showed mutational exclusivity in glioma." (PMID 29046615, 2017). "Furthermore, to evaluate whether KIF23 could act as an independent prognostic biomarker for glioma patients, we performed a stepwise, multivariate Cox regression analysis incorporating KIF23 expression, KPS score, age, tumor grade and IDH1 mutation status." (PMID 27013586, 2016). "Additionally, it has been demonstrated that 2-HG concentrations in serum specimens collected from patients with gliomas do not necessarily correlate with IDH1/2 mutation status or tumor size." (PMID 27014623, 2016). "In addition, BCAT1 was reported to promote cell proliferation in gliomas carrying wild-type IDH1." (PMID 27323413, 2016). "Indeed, those genes are important prognostic factors in glioma patients; in particular, IDH1 and IDH2 can be mutated in low-grade and anaplastic glioma, as well; in fact, mutations of IDH1 and IDH2 genes are found in 70% of grades II and III gliomas and secondary glioblastomas." (PMID 27493954, 2016). "Importantly, even though no PTEN mutations were observed in IDH1/2-mutated gliomas, the mTOR pathway is nonetheless frequently activated in these tumours." (PMID 27624942, 2016). "However, LDHA expression is typically silenced in mutant IDH1 gliomas, suggesting that pyruvate conversion to lactate could be reduced." (PMID 27144334, 2016). "Moreover, mutations of IDH1 and IDH2 are mutually exclusive in gliomas, and biochemical investigations showed that IDH1 and IDH2 mutations differ in D-2-hydroxyglutarate (D-2HG) production in gliomas." (PMID 27245697, 2016). "Interestingly, even though these metabolites presumably affect the same dioxygenases, mutations in IDH1/2 are linked to glioma and acute myeloid leukemia, but not to PGL/pheochromocytoma." (PMID 26294907, 2015). "The activating mutation is associated with 1p/19q codeletion and oligodendroglial histology in the presence of IDH1 mutation and identifies a subset of aggressive astrocytic tumors lacking IDH1 mutation, highlighting its potential diagnostic and prognostic impact in lower-grade gliomas." (PMID 26369702, 2015). "However, the IDH1 gene is rarely mutated in cancers other than gliomas and is therefore not a likely candidate as a causative factor for the CpG methylator phenotype in breast cancers." (PMID 25468711, 2015). "Mutant IDH1 anaplastic astrocytomas, glioblastomas and oligodendroglial tumors have independent favorable prognostic factor particularly for grade III gliomas, and usually associated with increased progression-free survival and overall survival and may exceed other genetic markers." (PMID 27275230, 2015). "IDH1 mutation is commonly present in adult gliomas particularly in low-grade gliomas, and secondary glioblastoma, with equal sex distribution, but it has no role in pediatric gliomas." (PMID 27275230, 2015). "Therefore, we may explain the lag in 5-ALA metabolism in IDH1 mutant malignant glioma cell lines by invoking alterations in NADPH metabolism." (PMID 26008980, 2015).
glioma (continued). "To determine whether IDH1-R132H could be a target for glioma immunotherapy we treated mIDH1-GL261 glioma-bearing mice with four short peptides (two 9-mers and two 10-mers) or one 16-mer peptide, all encompassing the IDH1 region encoding the mutation." (PMID 25849072, 2015). "Therefore, if there are metabolic changes linking IDH1 mutations and 5-ALA fluorescence, they may implicate important metabolic steps reflecting malignant transformation in gliomas." (PMID 26008980, 2015). "Likewise, although adult oligodendrogliomas frequently harbor detectable isocitrate dehydrogenase (IDH1) mutations, these mutations are almost always absent in pediatric gliomas." (PMID 25755903, 2015). "In addition, most low-grade gliomas lack 5-ALA fluorescence and harbor IDH1/2 mutations." (PMID 26008980, 2015). "Finally, urine protein levels of 2-hydroxyglutarate (2-HG) may aid in distinguishing IDH1 mutant glioma patients from those with IDH1 wild-type glioma." (PMID 25720744, 2015). "Within Grade III-IV gliomas, those patients with the TERT promoter mutations alone had the poorest prognosis (median 11.5 months), while tumors bearing the events typically representative of astrocytomas (IDH1/2 mutation) had a more favorable prognosis (median 56.9 months)." (PMID 24722048, 2014). "How mutations in IDH1 result in DNA methylation in gliomas is not entirely known." (PMID 25147764, 2014). "Utilizing an adult glioma dataset, Noushmehr and colleagues were able to subgroup tumors via DNA methylation profiling and identify a prominent G-CIMP subgroup defined by IDH1 mutation, which was later shown as detailed above, to be sufficient to create this phenotype." (PMID 25077668, 2014). "This study supports genotyping of TERT promoter and IDH1/2 in gliomas as a rapid economical test requiring little tumoral DNA that could help inform clinicians as to the predicted OS of these tumors that may differ from their predicted outcomes based on conventional histology alone." (PMID 24722048, 2014). "In addition, IDH1-R132H mutant-type GB may be indicative of a secondary GB progressing from low-grade glioma." (PMID 24765187, 2014). "No 2-HG was detected in 5 control glioma samples without IDH1 mutation." (PMID 24529257, 2014). "Combined with the clinical data, our findings indicate that increased PC expression and activity could be essential for survival of mutant IDH1 cells and, as such, could serve as a potential therapeutic target for mutant IDH1 gliomas either alone or in combination with other therapies." (PMID 25243911, 2014). "None of the IDH1/2 mutated gliomas had methylation of the TET2 promoter." (PMID 23998913, 2013). "Importantly, we show in that IDH1 (R132H) expression is stable through multiple passages, 2-HG is robustly produced in the tissue, and the model bears a hypermethylated CpG phenotype characteristic of IDH1 mutant glioma." (PMID 24077805, 2013). "Therefore, IDH1 may be used as a prognostic marker in low-grade and high-grade gliomas and aid in the differentiation and diagnosis of various tumors with histologic ambiguity." (PMID 23516171, 2013). "Therefore, we hypothesized that pre-treatment with 200 nM DAC may further ‘sensitize’ the IDH1-mutant glioma cells to the therapeutic effects of AGI-5198." (PMID 24077826, 2013). "IDH1/2 mutations, commonly found in adult secondary gliomas, are also not present." (PMID 22771539, 2013).